FKBPL (FKBP prolyl isomerase like)
Diseases named in the same sentence as FKBPL in open-access papers (continued):
Sharing a sentence is not in itself a finding about the gene and the disease.
FKBPL also shares sentences with these, for which no sentence is quoted: infection (7 papers); cardiovascular disease (3); bacterial diseases (2); ankylosing spondylitis (1); bipolar disorder (1); fungal infection (1); gestational diabetes (1); granulocytopenia (1); heart failure (1); Hodgkins lymphoma (1); lymphoma (1); myopathy (1); prostate carcinoma (1); schizophrenia (1); type 1 diabetes mellitus (1).